PALB2 (partner and localizer of BRCA2)
Diseases named in the same sentence as PALB2 in open-access papers (continued):
Sharing a sentence is not in itself a finding about the gene and the disease.
pancreatic cancer (continued). "PALB2 somatic PV occur in both pancreatic cancer and prostate cancer samples, whereas germline PV have been described in pancreatic cancer patients, at a slightly higher rate in high-risk compared to apparently sporadic patients (0.97% and 0.1–0.65%, respectively)." (PMID 35563100, 2022). "PALB2 has been reported as a susceptibility gene for pancreatic cancer." (PMID 35328658, 2022). "Also, truncating mutations in PALB2 were identified to occur in 1%–3% of familial pancreatic cancer cases." (PMID 34707985, 2021). "Heterozygous carriers of PALB2 mutations are at increased risk of breast and pancreatic cancers." (PMID 34461861, 2021). "PALB2 variants have also been associated with increased risk of ovarian and pancreatic cancers." (PMID 33917078, 2021). "BRCA1/2 and PALB2 are known to be associated with an increased risk for pancreatic cancer." (PMID 32793315, 2020). "In a logistic regression model adjusted for age at diagnosis and family history of cancer, ATM and BRCA2 mutations were associated with personal history of breast or pancreatic cancer, whereas PALB2 mutations were associated with family history of breast or pancreatic cancer." (PMID 31497750, 2018). "PALB2 germline mutations are rare in cases of pancreatic cancer." (PMID 27099641, 2016). "Interestingly, exome sequencing identified PALB2 as a pancreatic cancer susceptibility gene and PALB2 mutations have been found in patients with familial pancreatic cancers." (PMID 25869442, 2015). "PALB2 mutations were reported in 3/96 patients (3.1%) with familial pancreatic cancer." (PMID 25714017, 2015). "Notably, deleterious germline PALB2 mutations have also been reported in pancreatic cancer cohorts from United States and Europe, but its association with increased risk to ovarian cancer cohorts remains controversial." (PMID 23977390, 2013). "Mutations of PALB2 have been associated with familial breast cancer and pancreatic cancer." (PMID 23587053, 2013). "DNA damage repair deficiency, for example, through BRCA1/BRCA2, ATM or PALB2 loss, is seen in ∼15% of all pancreatic tumours and may represent a window of opportunity for radiotherapy in these patients due to increased radiosensitivity as a result of genomic instability." (PMID 38979684, 2024). "PALB2 mutation may also increase the risk of pancreatic cancer." (PMID 35779338, 2022). "Like BRCA1 and BRCA2 mutations, PALB2 mutation may increase the risk of pancreatic cancer." (PMID 35779338, 2022). "The observed dichotomy in precursor lesions between the Brca1-deficient and Brca2-deficient tumors and the mixture of both in Palb2 deficient tumors might provide insights into mechanisms underlying the higher pancreatic cancer incidence and aggressiveness in BRCA2 vs BRCA1 mutation carriers." (PMID 31877165, 2019). "The magnitude of pancreatic cancer risk conferred by PALB2 mutations also remains unclear." (PMID 26484312, 2015). "Pancreatic cancer cases with BRCA2/PALB2 germline alterations demonstrate a more enriched B cell population, including memory B cells and naïve B cells, and the abundance of B cells shows a positive correlation with the HRD score." (PMID 40830526, 2025). "PALB2, just like BRCA1/2, acts as a tumor suppressor, and pathogenic germline mutations increase the risk of breast, ovarian, and pancreatic cancers, underscoring its shared involvement in DNA repair." (PMID 41374970, 2025). "Pancreatic cancer cases with BRCA2/PALB2 germline alterations exhibit a more enriched population of activated NK cells." (PMID 40830526, 2025).
pancreatic cancer (continued). "The ongoing phase I/IIa PETRA trial (NCT04644068) has enrolled 61 patients with advanced HER2-negative breast, ovarian, prostate, or pancreatic cancer who had germline or somatic BRCA1/2, PALB2, or RAD51C/D loss-of-function mutations." (PMID 37588193, 2024). "Mutations in genes such as BRCA1, BRCA2, PALB2, and ATM are associated with an increased risk of pancreatic cancer, particularly in individuals with a family history of the disease." (PMID 39409171, 2024). "In familial pancreatic cancer (FPC), CDKN2A mutations, along with those in BRCA2 and PALB2, were prevalent, particularly in FPC probands, highlighting their significance in hereditary pancreatic cancer." (PMID 38666907, 2024). "The anticancer activity of PARP inhibitors in pancreatic cancer with mutations in HRR genes other than BRCA and PALB2 remains inconclusive." (PMID 39456541, 2024). "Patients with KRAS wild‐type disease and early‐onset pancreatic cancer (EOPC) harbored actionable mutations including BRAF, EGFR, ERBB2, and MAP2K1/2.PGVs in PALB2, BRCA2, and ATM were associated with high PDAC risk in the Chinese population." (PMID 36999792, 2023). "As discussed in a previous section, besides BRCA1 and BRCA2 mutations, mutations in PALB2, ATM, ATR, BRIP1, BARD1 and CDK12 are observed in low frequencies in pancreatic cancers." (PMID 36975505, 2023). "PALB2, BRCA2, and ATM PGVs were associated with high risks for pancreatic cancer in the Chinese population." (PMID 36999792, 2023). "Considering the relationship between aging, invasion, and metastasis of pancreatic cancer, it is crucial to consider ITGA2 mutation as significant as CDKN2A, BRCA1/2, and PALB2 mutations in the diagnosis and treatment of pancreatic cancer." (PMID 37881431, 2023). "Rucaparib was evaluated in a phase II trial as a maintenance regimen for advanced pancreatic cancer (including both metastatic and locally advanced cases) in patients harboring BRCA1, BRCA2 or PALB2 germline or somatic mutations." (PMID 37366887, 2023). "Three germline deleterious variations in cancer susceptibility genes, known as pancreatic cancer susceptibility genes (ATM, WRN, and PALB2), were identified in our study population." (PMID 37313463, 2023). "Protein‐truncating variants in three DNA damage repair genes (PALB2, BRCA2, and ATM) were associated with a significant risk of pancreatic cancer (p < 0.05), with odds ratio ranging from 5.03 to 10.03." (PMID 36999792, 2023). "Previous studies have described a responsiveness to platinum agents in pancreatic cancer patients with PALB2 GPVs and ovarian cancer patients with GPV in HR genes." (PMID 35806485, 2022). "Glutamyl-tRNA synthetase 2 (EARS2) was the only gene coexpressing with PALB2 in the breast and pancreatic cancer subjects that was significantly related to worse pancreatic cancer survival." (PMID 35779338, 2022). "Using the Cancer Genome Atlas (TCGA) and The Human Protein Atlas we examined genes that co-express with PALB2 in breast and pancreatic cancer." (PMID 35779338, 2022). "The selected pancreatic cancer patients with BRCA1/2 and PALB2 mutations and HRD are included in this study." (PMID 35328658, 2022). "Over the last decade, the genetics associated with pancreatic cancer has been intricately assessed Some well-known cancer gene germline mutations have been identified in patients with pancreatic cancer, including BRCA1/2, PALB2, STK11, PRSS1, SPINK1 and ATM." (PMID 35813042, 2022). "A phase II study evaluated maintenance rucaparib in patients with platinum-responsive pancreatic cancer and a pathogenic germline and somatic variant in BRCA1, BRCA2, or PALB2." (PMID 35163129, 2022).
pancreatic cancer (continued). "Glutamyl-tRNA synthetase 2 (EARS2) was the only gene coexpressing with PALB2 in the breast and pancreatic cancer subjects that was significantly related to pancreatic cancer survival." (PMID 35779338, 2022). "A phase II, single-arm study evaluating the role of rucaparib as the maintenance therapy for advanced pancreatic cancer with the germline or somatic mutations in BRCA1, BRCA2, or PALB2 enrolled 46 patients, 42 of whom were eligible for the evaluation." (PMID 36556296, 2022). "Six genes, EARS2, ARL6IP1, DNAJA3, KNOP1, RPUSD1, and TMEM186, significantly coexpressed with PALB2 in both breast and pancreatic cancer." (PMID 35779338, 2022). "There is also a suggestive case report showing a potential involvement of GPVs of PALB2 and NBS1 (NBN) in the susceptibility to pancreatic cancer." (PMID 35008774, 2021). "In a large cohort comprising 2,818 sporadic pancreatic cancers, our group identified gene mutations in BRCA1, BRCA2, or PALB2 in 1.3%, 3.1%, and 0.6%, respectively." (PMID 34707985, 2021). "Various PALB2 mutations are involved in HBOC predisposition, particularly associated with breast and pancreatic cancers, whereas few studies have reported PALB2 variants in HPCa patients." (PMID 33916521, 2021). "Further, in mouse models of pancreatic cancer, BRCA2 mutations are associated with an immune ‘desert’ phenotype, while PALB2 mutant models show intermediate infiltration by immune cells." (PMID 34572943, 2021). "A deleterious germline mutation in the PALB2 (Partner and Localizer of BRCA2) gene, which accounts for 3–4% of familial pancreatic cancer cases, was identified in a 53‐year‐old female patient." (PMID 33350171, 2021). "The American College of Medical Genetics and Genomics (ACMG) recommends that PALB2 gene testing should be included in the test panel for breast, ovarian, and pancreatic cancer." (PMID 34439348, 2021). "In 2009, Jones and colleagues carried out exomic sequencing of PALB2 gene in 96 familial pancreatic cancer (FPC) patients in USA, thus identifying 3 truncating PVs producing different stop codons." (PMID 33718150, 2021). "Here, we present the case of a female patient harboring pathogenic variants of PALB2 and NBN, with a family history of multiple pancreatic cancer in her younger brother, her aunt, and her father." (PMID 33413558, 2021). "This surveillance is also recommended for individuals with three or more blood relatives with pancreatic cancer, and at least one of those affected FDR carrying the BRCA2 or PALB2 germline pathogenic variant." (PMID 34476650, 2021). "PALB2 (partner and localizer of BRCA2) is also involved in DNA damage repair and Fanconi anemia, which is strongly associated with breast, ovarian, and pancreatic cancer." (PMID 34476650, 2021). "Retrospective studies suggest a survival benefit when platinum-based chemotherapy is administered to patients with pancreatic cancer harbouring a germline mutation in BRCA1, BRCA2 or PALB2 (mut-positive PDAC)." (PMID 31787751, 2020). "Subsequent studies also revealed the prevalence of PALB2 deleterious mutations in patients with FPC (~3–4%), validating the role of PALB2 mutations in pancreatic cancer predisposition." (PMID 32185139, 2020). "These deceased participants had actionable findings in PALB2 and TSC2 indicating breast and pancreatic cancer risk and tuberous sclerosis type II, respectively." (PMID 32377377, 2020). "As PALB2 mutations also have been observed in families with breast, ovarian and pancreatic cancer like BRCA1/2, the PALB2 gene has also been recognized as a tumor susceptibility gene." (PMID 31877165, 2019).
pancreatic cancer (continued). "Alterations of the PALB2 tumor suppressor gene have been identified in familial breast, ovarian and pancreatic cancer cases." (PMID 31877165, 2019). "An estimated 5~10% of pancreatic cancer is familial, with breast cancer susceptibility genes 1/2 (BRCA1/2) and partner and localizer of BRCA2 (PALB2) among established pancreatic susceptibility genes." (PMID 31877165, 2019). "Like BRCA1 (FANCS) and BRCA2 (FANCD1), monoallelic mutations in PALB2 confer familial susceptibility to breast, ovarian and pancreatic cancer, while biallelic PALB2 lesions cause Fanconi anemia (FA) subtype N (FANCN)." (PMID 31877165, 2019). "We compared the histo-pathology of the pancreatic tumors that developed among Palb2-KPC, Brca1-KPC and Brca2-KPC to those of KPC animals." (PMID 31877165, 2019). "Villarroel and colleagues (2011) described a pancreatic cancer patient that had a long-lasting response to mitomycin C (MMC, a crosslinking agent) treatment and whose tumor was deficient for PALB2." (PMID 28858227, 2017). "The study included 178 CDKN2A mutation carriers, 214 individuals with familial pancreatic cancer, and 19 BRCA1/2 or PALB2 mutation carriers." (PMID 29069866, 2017). "This is clear from the differing reports relating PALB2 to breast and pancreatic cancer development." (PMID 24949998, 2014). "In another study, the screening of 254 pancreatic cancer cases, including 101 with a family history of the disease, led to the report of a 6.7 kb deletion of PALB2 in an individual with both breast and pancreatic cancer." (PMID 24949998, 2014). "Considering these two PALB2 variants as causal mutations, the prevalence of PALB2 mutation in our BRCA1/BRCA2 breast and pancreatic cancer series is 1.5% (2/132)." (PMID 23935836, 2013). "In agreement with BRCA2-related function of the PALB2, pancreatic cancer xenografts obtained from a PALB2 carrier demonstrated pronounced sensitivity to cisplatin and mitomycin C." (PMID 21819606, 2011). "PALB2 (Partner And Localizers of BRCA2) has been proven to cause breast and pancreatic hereditary cancer." (PMID 21819606, 2011). "Homologous recombination deficiency (HRD) arising from BRCA1or BRCA2 or PALB2 mutations confers sensitivity to platinum chemotherapy and PARP inhibition in pancreatic cancer (PC) and may enable prolonged disease control with immune checkpoint blockade (ICB)." (PMID 41882405, 2026). "Additionally, young-onset PC (in patients younger than 50 years old) shows higher proportions of MSI-high/dMMR, BRCA2-mutant, and PALB2-mutant tumors compared with patients with average-onset pancreatic cancer (70 years and older)." (PMID 41374970, 2025). "The Hereditary Breast, Ovarian, and Pancreatic Cancer Variant Curation Expert Panel (HBOP VCEP) has undertaken the process for creating gene- and disease-specific specifications for the interpretation of PALB2 germline sequence variants." (PMID 40967221, 2025). "Genetic syndromes, such as those resulting from inherited mutations in genes like STK11, BRCA1, BRCA2, PALB2, CDKN2A, and DNA repair genes, notably elevate the risk of pancreatic cancer, particularly in individuals with a family history of pancreatic cancer among first-degree relatives." (PMID 39949443, 2025). "Compared with wild-type (WT) tumors, significantly more adaptive immune response cells, especially tumor-infiltrating lymphocytes (TILs), are enriched in BRCA1/2 mutant TNBC, as well as prostate cancer and pancreatic cancer with BRCA2, PALB2, or ATM germline mutations." (PMID 40830526, 2025).
pancreatic cancer (continued). "In addition, Case 2 exhibited a deletion of the PALB2 gene and a BRCA1 (D695Y) mutation with a family history of cancer affecting four members, including one diagnosed with pancreatic cancer." (PMID 40283643, 2025). "CAPS recommends pancreatic cancer screening beginning at the age of 50 years or 5 years earlier than for high-risk individuals with defined familial pancreatic cancer in patients with BRCA2, ATM, and PALB2 mutations (Grade 2: probably do it)." (PMID 39200847, 2024). "Furthermore, the NCCN guidelines also recommended somatic testing of KRAS, BRAF, HER2, PALB2, MMR deficiency, and oncogenic gene fusions for pancreatic cancer patients with advanced or metastatic diseases." (PMID 36999792, 2023). "A similar randomized phase II trial of maintenance olaparib in resected pancreatic cancer and pathogenic BRCA1/BRCA2 or PALB2 mutations (ECOG-ACRIN EA2192, APOLLO) is enrolling patients with either germline or somatic mutations who have received 3 to 6 months of peri-operative chemotherapy." (PMID 36975505, 2023). "The new guidelines may improve treatment as well as prognosis, since PALB2 protein expression is an unfavorable marker in pancreatic cancer." (PMID 35779338, 2022). "For example, the DDR genes BRCA1, BRCA2 and ATM, or PALB2, each one usually found mutated in no more than 3.5% of cases, increase pancreatic cancer risk when altered at the germline level." (PMID 35563100, 2022). "PALB2 is reported to occur in 2-4.9% of familial pancreatic cancer patients and 0.5% sporadically." (PMID 35228986, 2022). "NCT03140670 is a phase II trial of rucaparib evaluating patients with advanced pancreatic cancer with known germline or somatic BRCA or PALB2 mutations who had not progressed on at least 16 weeks of platinum treatment." (PMID 35228986, 2022). "PALB2 causes Fanconi’s anemia by biallelic germline loss-of-function mutations (also known as FANCN); whereas monoallelic loss-of-function mutations are linked to an elevated risk of breast and pancreatic cancer." (PMID 35779338, 2022). "The efficacy of platinum agents for pancreatic cancer with a germline BRCA/PALB2 mutation and of olaparib, a poly (ADP-ribose) polymerase (PARP) inhibitor, as maintenance therapy after first-line platinum-based chemotherapy for pancreatic cancer with germline BRCA1/2 have been shown." (PMID 33557084, 2021). "Furthermore, recent studies have reported that BRCA1/2 pathogenic variants potentially contribute to FPC and that the frequency of BRCA1/2, PALB2, and ATM variants in all pancreatic cancers is 7%." (PMID 33413558, 2021). "However, in pancreatic cancer, only germline BRCA1/2 and PALB2 mutation, microsatellite instability, and NTRK fusions have gained general acceptance as actionable alterations by experts in the field." (PMID 33350171, 2021). "Further, BRCA1, BRCA2 and PALB2 mutant pancreatic cancer frequently shows signature 3, and the presence of signature 3 is predictive of response to platinum chemotherapy in patients with advanced pancreatic cancer." (PMID 34572943, 2021). "MGPTs generally cover at least 10 common HR-related genes such as ATM, BARD1, BRCA1, BRCA2, BRIP1, CHEK2, NBS1 (NBN), PALB2, RAD51C, and RAD51D, all of whose germline alterations are associated with BRCAness phenotypes for predisposition to breast, ovarian, prostate, or pancreatic cancer." (PMID 35008774, 2021). "Familial pancreatic cancer mutations residues are located mostly on BRCA1, BRCA2, p16, PALB2 genes." (PMID 32774122, 2020).